INS (insulin)
Diseases named in the same sentence as INS in open-access papers (continued):
Sharing a sentence is not in itself a finding about the gene and the disease.
prostate carcinoma (continued). "Prostate cancer patients present a promising cohort for the exploration of insulin stabilising agents as adjunct treatments for hormone deprivation or enhancers of chemosensitivity for treatment of advanced prostate cancer." (PMID 22548055, 2012). "Our findings suggest a role of the insulin signaling pathway in prostate cancer and surrounding tissue and can hence be relevant for both novel diagnostic and therapeutic approaches in this malignancy." (PMID 23251408, 2012). "We found significant differences in the insulin signaling cascade between benign prostate tissue and prostate cancer." (PMID 23251408, 2012). "J. Hammarsten and B.Högstedt prospectively assessed baseline insulin levels at time of prostate cancer diagnosis and compared them between men who died from prostate cancer during 5 years of followup and men who survived." (PMID 22548055, 2012). "Leptin and insulin/IGF-1 are high in obese men and suppress androgen levels, moreover leptin has been implicated in advanced and high-grade prostate cancer in two case–control studies." (PMID 21266978, 2011). "It is reported that a high protein diet is detrimental to renal functions and insulin sensitivity, and related to prostate cancer and calcium oxalate nephrolithiasis." (PMID 21151458, 2010). "The principal outcome of this project will be the determination of the strength of effect of exercise on the well established musculoskeletal, cardiovascular and insulin metabolism side effects of androgen deprivation in prostate cancer patients." (PMID 19563641, 2009). "The principal outcome of this project will be the determination of the strength of effect of exercise on the well established musculoskeletal, cardiovascular and insulin metabolism side effects of ADT in prostate cancer patients." (PMID 19563641, 2009). "In particular, we observed that by integrating information from the insulin signalling pathway into our prediction model, we achieved better prediction of prostate cancer." (PMID 19458772, 2007). "In this report, we demonstrate that DCPA inhibited the migration and proliferation of DU145 and PC-3 prostate cancer cells induced by serum, insulin, and insulin-like growth factor I (IGF-I)." (PMID 16884534, 2006). "The relationship between increased insulin level and advanced tumour stage in prostate cancer we describe here is biologically quite plausible, since insulin is a growth factor." (PMID 12232754, 2002). "Since insulin is believed to be a growth factor for prostate cancer, it has been hypothesized that reducing carbohydrate intake would result in lower insulin levels, slowing the growth of cancer cells." (PMID 39954205, 2025). "Elevated insulin levels can induce chronic low-grade inflammation and oxidative stress, which promote the formation of a tumor microenvironment and enhance the aggressiveness of prostate cancer." (PMID 40864064, 2025). "Numerous metabolic imbalances and interrelated pathways, including altered sex steroid hormones, serum insulin levels, and free insulin-like growth factor 1 levels may influence prostate cancer prognosis." (PMID 39180334, 2024). "Similarly, a nationwide Danish cohort study reported a lower incidence of prostate cancer in individuals using GLP-1RAs compared to those on basal insulin, particularly in older adults and those with preexisting CV disease." (PMID 39595655, 2024). "Mechanisms linking physical activity with specific cancer sites have been proposed, including its effects on sex hormones (breast, endometrial and prostate cancers), insulin sensitivity, glucose metabolism and adipokines (obesity-related cancers), and inflammation and immune function (most cancers)." (PMID 38609941, 2024). "In addition, insulin promotes the migration of neural cells, thyroid cells, vascular smooth muscle cells, and advanced prostate cancer (PCa)." (PMID 36975518, 2023).
prostate carcinoma (continued). "Additionally, in patients receiving an androgen-lowering therapeutic regimen for the treatment of prostate cancer, the amount of visceral fat and insulin resistance increases under this therapy." (PMID 34223999, 2022). "Signaling pathways activated by insulin are altered in cancer cells, including prostate cancer." (PMID 33921222, 2021). "Protein restriction improves insulin and leptin sensitivity in patients with prostate cancer." (PMID 34766923, 2021). "In another in vitro study, insulin via the upregulation of Forkhead Box Protein C2 (FOXC2) promotes migration and invasion of prostate cancer cells and activation of insulin signaling pathway and inhibition of PI3K and MAPK pathways lead to epithelial-mesenchymal transition." (PMID 33921222, 2021). "Intriguingly, data from a previous study have shown that insulin is a proliferation factor for prostate cancer; thus, the reduction of carbohydrates may subsequently decrease serum insulin and slow down prostate cancer proliferation." (PMID 29643982, 2018). "A large population-based prospective cohort study (Prostate Cancer data Base Sweden, PCBaSe) on prostate cancer in T2D patients reported a decreased cancer risk only for insulin and sulfonylurea users but not for MTF users (HR 0.96, 95% CI 0.77–1.19)." (PMID 30241339, 2018). "Nevertheless, this difference between the risk associations between HbA1c and fasting glucose suggests that the interaction between blood glucose, insulin and prostate cancer may be complex." (PMID 29563633, 2018). "Compared to men not treated with anti‐diabetic drugs, men on metformin had no increased risk of prostate cancer (HR = 0.96, 95% CI = 0.77–1.19), whereas men on insulin (89%) or sulfonylurea (11%) had a decreased risk (HR = 0.73, 95% CI = 0.55–0.98)." (PMID 27770555, 2017). "In the subgroup of men with T2DM with more than 1 year disease duration, we found no decrease in risk of prostate cancer for men on metformin and a weak decrease in risk for men on insulin/sulfonylurea compared to men with T2DM not on anti‐diabetic drugs." (PMID 27770555, 2017). "In addition, evidence from population-based screening cohorts has demonstrated that both insulin and IGF-1 levels correlate more closely than PSA levels with the risk of developing prostate cancer." (PMID 27599544, 2016). "The protective mechanism of physical activity on the survival of prostate cancer patients is likely attributable to the influence of various hormones, such as insulin and androgens, and other growth factors that are related to the aggressiveness of prostate cancer." (PMID 26996776, 2016). "Further, it should be noted that neither oral antidiabetic medications (sulfonylurea and thiazolidinedione) nor insulin use was associated with advanced prostate cancer (data not shown in tabular format)." (PMID 27547763, 2016). "In addition, the overlapped targets of miR-196a were enriched in several pathways including glioma, focal adhesion, ECM–receptor interaction, gap junction, prostate cancer, GnRH signaling pathway, melanogenesis, and insulin signaling pathway." (PMID 26805888, 2016). "The pathway annotations via the KEGG pipeline indicate insulin signaling and prostate cancer pathways while the manual annotations point to transforming growth factor beta (TGF-beta) SMAD dependent signaling, for which this and other FOX members are interacting co-factors/co-activators of SMADs." (PMID 27602200, 2016). "The reduction in the insulin level may be one of the mechanisms by which metformin additively decreased prostate cancer tumor size in vivo, because insulin is one of the growth factors of prostate cancer cells, as we have previously demonstrated." (PMID 26439622, 2015). "Our results also support the hypothesis that high insulin concentrations might be able to activate mechanisms that increase cell survival and prostate cancer progression after androgens inactivation therapy or in castration-resistant forms." (PMID 25928422, 2015).
prostate carcinoma (continued). "Long-acting insulin therapy also decreased the risk of developing lung (AHR = 0.51 (0.31–0.86)), liver (AHR = 0.66 (0.47–0.93)), colorectal (AHR = 0.40 (0.24–0.69)), and prostate cancer (AHR = 0.12 (0.30–0.49)) (all p<0.05)." (PMID 25978841, 2015). "However, the mechanisms of action of insulin in the specific context of prostate cancer (PCa) and, in particular, the specific receptor that mediates its actions have not been elucidated yet." (PMID 24434591, 2014). "Furthermore, increased insulin signalling would be facilitated by increased INSR expression in advanced prostate cancer (Lubik, Gunter, Nelson, unpublished data)." (PMID 23573093, 2013). "Baseline insulin levels at time of prostate cancer diagnosis have also been shown to be the most significant predictor of lethal prostate cancer, strongly suggesting that insulin is a major factor in prostate cancer progression associated with metabolic dysfunction." (PMID 23573093, 2013). "The ability of insulin to accelerate de novo steroid synthesis in prostate cancer cells suggests that drugs targeting steroidogenesis in combination with insulin-lowering therapies would be beneficial; trials combining abiraterone and metformin are yet to commence (NCT01677897)." (PMID 23573093, 2013). "So far, only one study in prostate cancer has examined serum insulin levels using fasting blood." (PMID 12610512, 2003). "Our data suggest that the insulin gene plays a role in the aetiology of prostate cancer." (PMID 12610512, 2003). "Further studies may document whether serum insulin level might be a useful biomarker of prostate cancer stage." (PMID 12232754, 2002). "Further studies may document whether serum insulin levels might be a useful biomarker of prostate cancer stage." (PMID 12232754, 2002). "But there has been little investigation into the role insulin itself plays in prostate cancer." (PMID 12232754, 2002). "In a previous study, we measured insulin levels in men with prostate cancer." (PMID 12232754, 2002). "Moreover, an RCT in prostate cancer patients demonstrated that reductions in insulin following preoperative HIIT were independent of weight loss." (PMID 40895542, 2025). "In our study, elevated levels of insulin and IGF-1 in the PCa-DM group are positively correlated with the prostate cancer grade and risk, supporting the hypothesis that the mitogenic and oncogenic roles of insulin and IGF-1 might be associated with cancer aggressiveness in the diabetic group." (PMID 41367482, 2025). "Serum insulin and insulin-like growth factor-1 were significantly elevated in benign prostatic hyperplasia and prostate cancer group compared to controls with highest values in prostate cancer group (p-value <0.002 for insulin, <0.001 for insulin-like growth factor-1 and <0.014 for testosterone)." (PMID 39781138, 2024). "Additionally, dietary protein might decrease the sensitivity of insulin and boost the growth of prostate cancer cells in animal models, which in turn affects PSA levels." (PMID 36950094, 2023). "Toxic effects induced by exposure to 1-DSA have been reported in different cell types, including insulin-producing β-cells, pancreatic acinar cells, and peripheral neurons, mouse embryonal fibroblasts (MEFs), pig kidney epithelial cells and human prostate cancer cells." (PMID 35002962, 2021). "However, the evidence linking insulin sensitivity to prostate cancer risk is inconclusive due to a lack of high-quality studies investigating this." (PMID 34822385, 2021). "Moreover, a growth factor structurally similar to insulin peptide, called Insulin Like Growth factor type 1 (IGF-1), is inversely associated with all-cause mortality in men affected by prostate cancer if fact it is a candidate prognostic marker in patients affected by advanced disease." (PMID 28389628, 2017).
prostate carcinoma (continued). "Therefore, the main goal of our study was to assess the effects of preadipocyte and adipocyte secreted factors in the proliferation, migration and invasiveness of prostate cancer cells, and the effects of the adiposity signals, insulin and leptin, in cell proliferation." (PMID 25928422, 2015). "Some limited in vitro evidence suggests a direct link between the IGF-1/insulin axes and vitamin D. For example, laboratory studies on cultured the human prostate cancer cells the LNCaP human prostate cancer cell line have suggested that 1,25-dihydroxyvitamin D3 might influence IGFBP-3 levels." (PMID 22216097, 2011). "Moreover, insulin is necessary for the growth of prostate cancer cells in culture." (PMID 12232754, 2002). "Correlation of PSA, insulin, IGF-1 and testosterone with other influencing parameters in prostate cancer group." (PMID 39781138, 2024). "Significantly, VCAM1 expression was elevated in vascular endothelial cells under the stimulation of IL-17 and insulin/IGF1, which strengthened the adhesion between PCa cells and vascular endothelial cells and promoted prostate cancer metastasis." (PMID 37494663, 2023). "One study suggested a link between fat intake and prostate cancer involving IGF‐1, insulin, or leptin." (PMID 34606688, 2021). "Increasing evidence in prostate cancer and PCOS has revealed cross-talk between androgen and insulin signaling or its downstream cell proliferation pathways 36-38." (PMID 32913460, 2020). "Our objective was to evaluate if there is any correlation between IR (through the mediation of dermcidin protein, NO, HOMA score, Insulin, HDL) and status of prostate cancer outcome which is evaluated as health status." (PMID 31300527, 2019). "We prospectively studied men in the comparison cohort in the Prostate Cancer data Base Sweden 3.0, with data on T2DM, use of metformin, sulfonylurea and insulin retrieved from national health care registers and demographic databases." (PMID 27770555, 2017). "In the case of human prostate cancer cell lines (PC3 and LNCaP), 24‐hrs treatment with IGF1 and insulin reduced (or tended to reduce) the expression of IGF1R, INSR and GHR, whereas only insulin increased the expression levels of Igfbp3 in LNCaP cells." (PMID 28244645, 2017). "Dietary-induced hyperinsulinemia via excessive consumption of carbohydrate food sources has been shown to increase levels of IGF-1 and activate the insulin pathway and AKT, increasing prostate cancer growth in mouse studies." (PMID 26977321, 2016). "Insulin and IGF1 enhance IL-17-induced inflammatory responses through suppressing GSK3, leading to enhanced prostate cancer formation in obese mice." (PMID 26871944, 2016). "Insulin treatment up-regulated PKM2 in H1299 (lung cancer) and PC3 (prostate cancer) cells also, replicating the observations made in HepG2 cells." (PMID 23837608, 2013). "For example, a special serum-free defined medium that can support short-term, long-term, and clonal growth of the human prostatic carcinoma cell lines LNCaP, DU 145, PC-3, and ALVA-31 must contain insulin." (PMID 12232754, 2002). "Systemic insulin, IGF-1 and other biomolecules (e.g., HIF-1, VEGF, etc.)may modify ADSCs homeostasis within PPAT, with further effects on prostate cancer biology." (PMID 39941741, 2025). "The various signalling pathways that were identified include: PI3K-Akt, Prostate cancer, Ras, Chemokine, HIF-1, FoxO, sphingolipid, AMPK, VEFG, JAK-STAT, insulin, GnRH, oestrogen, prolactin, thyroid hormone, relaxin, progesterone-mediated oocyte maturation, and progesterone." (PMID 39114070, 2024).
prostate carcinoma (continued). "The enrichment pathways identified following KEGG analysis that contained the most core targets included prostate cancer, the HIF-1 signaling pathway, insulin resistance, the IL-17 signaling pathway, the PI3K-Akt signaling pathway, the TNF signaling pathway, and more." (PMID 38612466, 2024). "Serum insulin and insulin-like growth factor-1 showed non-significant positive correlation, whereas testosterone showed non-significant negative correlation with prostate cancer Gleason score and grade." (PMID 39781138, 2024). "Lower risks of breast (n = 15; RR = 0.90; 95% CI = 0.82–0.98) and prostate cancers (n = 7; RR = 0.74; 95% CI = 0.56–0.98) were found among insulin users compared with nonusers." (PMID 37481610, 2023). "Given the differences in circulating insulin levels, a known regulator of cell growth, we hypothesized that systemic CAMKK2 could promote prostate cancer cell growth and disease progression in part through cancer cell-extrinsic mechanisms." (PMID 35741020, 2022). "In prostate cancer cells, miR-26b can inhibit autophagy by targeting ULK2, while ULK2 is found not essential for autophagy induction in adult hippocampal neural stem cells following insulin withdrawal." (PMID 36387235, 2022). "Here, we investigated the effects of gintonin on insulin release in INS-1 rat pancreatic beta cells and on cell migration of PC-3 prostate cancer cells, to elucidate whether gintonin can also act on GPR40 and GPR55." (PMID 32121640, 2020). "We, herein, investigated whether gintonin could serve as a ligand for GPR40 and GPR55, using the insulin-secreting beta cell-derived cell line INS-1 and the human prostate cancer cell line PC-3, respectively." (PMID 32121640, 2020). "Besides, because anticarcinogenic properties of naringenin have been reported in diverse malignant tumors prostate cancer pathway consisting of eight proteins was found: AKT1, MAPK1, IGF1R, AR, CCND1, INS, PIK3CA, IGF1." (PMID 30918758, 2019). "However, in response to growth factor/amino acids stimulation, LARP1 knockdown significantly delayed and attenuated phosphorylation of these proteins in HEK293T cells, LnCap (prostate cancer cell line), and HEK293E cells (insulin sensitive)." (PMID 28650797, 2017). "One hypothesis is that indirect insulin lowering effect may have an anti-neoplastic effect as elevated insulin and insulin like growth factor − 1 (IGF-1) levels play a role in prostate cancer development and progression." (PMID 28732480, 2017). "Leptin, an hormone activating the same pathway of insulin and IGF-1, stimulate survival of prostate cells hormone independent and increased blood levels of leptin were observed in patients with an aggressive biology of prostate cancer." (PMID 28389628, 2017). "Insulin and IGF1 enhanced IL-17-induced inflammatory responses through suppressing GSK3, which was shown in the cultured cell lines in vitro and obese mouse models of prostate cancer in vivo." (PMID 26871944, 2016). "Furthermore, we have previously reported that insulin and insulin-like growth factor–1 (IGF–1) accelerate prostate cancer cell proliferation through androgen receptor (AR) activation by disrupting its direct interaction with Foxo1." (PMID 26439622, 2015). "Interesting pre-clinical data also exist for the combination of insulin/IGF system inhibitors with other drugs, including the lipid modulator simvastatin in prostate cancer, the VEGF antibody bevacizumab in ovarian cancer, and methyl jasmonate in endometrial cancer." (PMID 26029167, 2015).